CCL5 (C-C motif chemokine ligand 5)
Diseases named in the same sentence as CCL5 in open-access papers (continued):
Sharing a sentence is not in itself a finding about the gene and the disease.
tumor (continued). "In solid tumors, overexpressing CCL5 by tumor cells will lead to the recruitment of Treg and establishment of local immunosuppression." (PMID 36031660, 2022). "Knockdown of KRT23 expression in tumor cells resulted in increased secretion of CCL5 and inhibited tumor cell proliferation." (PMID 35814465, 2022). "In cHL, mast cells are present at high frequencies, promoting fibrosis and HRS cell growth, while mast-attracting factors such as CCL5 are released by tumor cells simultaneously." (PMID 35267668, 2022). "Studies have shown that CCL5 expression is much higher in parental tumour tissue than in radioresistant tumour tissue." (PMID 35365161, 2022). "The engineered oHSV also expresses chemokine CCL5, which will help to attract endogenous tumor infiltration T cells and CAR T cells to traffic to the tumor sites." (PMID 36353540, 2022). "Intriguingly, the high expression of CCL5 in tumor buds at the invasive front was often accompanied by increased collagen synthesis." (PMID 35241150, 2022). "In the tumor microenvironment, it has also been demonstrated that M-MDSCs generated in the BM that migrate to the tumor site are attracted by local CCL5 production." (PMID 36430701, 2022). "Increasing evidence suggests that signaling from CCR5 and its ligand, C-C motif chemokine ligand 5 (CCL5), determines the immunosuppressive phenotypes of a huge proportion of immature myeloid cells, including MDSCs, at tumor-bearing sites." (PMID 36361830, 2022). "Infused NK cells were engineered to overexpress CCR5, and a vaccinia virus armed with CCL5 was injected intratumorally, resulting in increased NK cell infiltration and tumour regression." (PMID 35205725, 2022). "CCL5 is an angiogenic chemokine, and CCL5/CCR5 axis is notably involved in VEGF-mediated tumor angiogenesis." (PMID 35784739, 2022). "Meanwhile, studies reported tumor and stromal cells in the tumor microenvironment release chemokines (for instance, CCL2 and CCL5) and cytokines (such as CSF-1 and VEGF), recruiting circulating monocytes, resulting in tumor-associated macrophages (TAMs)." (PMID 36421355, 2022). "It was found that after the expression of CCL5 was blocked by gene knockout, the recruitment of Tregs into the tumor microenvironment was slowed, thus effectively reducing the proliferation of tumor cells." (PMID 35145917, 2022). "Romidepsin induced the secretion of various chemokines from tumor cells, such as CCL5, CXCL9 and CXCL 10, attracting T lymphocytes into the tumor." (PMID 36080223, 2022). "LMP1 can activate PI3K/AKT and HIF-1α signaling pathways in EBV-positive NPC cells and function in chemokine ligand 5- (CCL5-) mediated tumor angiogenesis." (PMID 36438903, 2022). "CCL5 is known to be a key factor in the tumor microenvironment, especially in recruiting monocytes and promoting macrophage function." (PMID 35033156, 2022). "In conclusion, the present study suggests that at the invasive front of CRC, tumor bud-derived CCL5 can recruit fibroblasts via CCR5-SLC25A24 signaling." (PMID 35241150, 2022). "Increased secretion of RANTES (CCL5) by natural killer cells in the tumor microenvironment is noted in this pathway, and RANTES was found to be elevated in BCW12OFS tumors." (PMID 35681702, 2022). "We uncovered a novel anti-tumor role of RUNX3 in suppressing Ccl5 expression in lung-resident NK cells." (PMID 36231078, 2022). "The CD27-positive, CD38-positive, and PAX5-negative tumor-induced plasmablast-like-enriched B cell (TIPB) population regulates T cell-recruiting chemokines (CCL3, CCL4, and CCL5) and increases the number of tumor-infiltrating T cells." (PMID 36361781, 2022). "Genetic variation in single nucleotide polymorphisms (SNPs) of CCL5 and CCR5 in patients with mCRC predicts the efficacy of the anti-epidermal growth factor receptor based on the location of the tumor." (PMID 36387070, 2022).
tumor (continued). "Most studies have concluded that CCL5 promotes tumor progression, but its antitumor effects are evident in specific tumor microenvironments, particularly in TME infiltrated by large numbers of CD8+ T cells." (PMID 36387070, 2022). "CCL5 is expressed in T lymphocytes, macrophages, platelets, synovial fibroblasts, the tubular epithelia, and tumor cells." (PMID 35241150, 2022). "The secretome of MSCs is variable but mostly CCL2, CCL5, IL-6, TGFβ, VEGF which have been implicated in tumor growth and/or metastasis are commonly expressed." (PMID 35150338, 2022). "The dual ability of CCL5 to provide carcinogenesis or antitumor adjuvanticity depending on the tumor environment appears to be justified by the type of cancer, CCR5 expression and localization of CCL5 expression." (PMID 36430633, 2022). "CCL5, as a receptor antagonist, plays a positive role in the process of tumour progression by attracting macrophages." (PMID 36160018, 2022). "Radiation combined with vaccination upregulates the expression of the chemokines CXCL10 and CCL5 in the tumour, along with increased CD8+ T cell infiltration." (PMID 35365161, 2022). "Within the tumor and its microenvironment, the enhanced levels of CCL5 activate the PI3K/AKT/mTOR pathway and lead to cellular proliferation and resistance to apoptosis." (PMID 36430633, 2022). "One notable function of tumor associated eosinophils is their expression of chemokines, such as CXCX9, CXCL10 and CCL5, which further recruit CD8+ CTLs to the tumor sites." (PMID 36231078, 2022). "Accordingly, tumor bud-derived CCL5 can further promote angiogenesis and collagen synthesis through fibroblasts, and eventually, create a tumor-promoting microenvironment." (PMID 35241150, 2022). "CCL5 induced tumor immune tolerance by recruiting and regulating the activity of inflammatory cells such as T cells." (PMID 35145917, 2022). "We believe that high expression of CCL5 in tumor sites is more likely to be a representative marker." (PMID 36387070, 2022). "CCL5 plays a role in the chemoattraction and activation of immune cells, and it enhances tumor infiltration by immune cells." (PMID 35320940, 2022). "Chemokines secreted by tumor cells, such as C-C Motif Chemokine Ligand 2, C-C Motif Chemokine Ligand 5, and colony stimulating factor 1, can recruit M2-type tumor-associated macrophages, and their abundance in TME correlates with a poor prognosis." (PMID 35720039, 2022). "The expression of CCL5 in tumor tissue and serum was measured with a Luminex protein detection kit, and the correlation between CCL5 and clinical parameters was evaluated." (PMID 36033472, 2022). "FAK signaling create the immunosuppressive TME by regulating the expression of chemokines such as CXCL12 and CCL5, enabling tumors to escape anti-tumor immunity." (PMID 35425701, 2022). "As a key mediator of immune recruitment in tumor tissues, CCL5 is highly expressed in plasma cells and cancer cells." (PMID 36148946, 2022). "A previous study demonstrated that CCL5 promoted T cell infiltration and inhibited tumor progression." (PMID 36428599, 2022). "Taken together, these results suggested that tumor buds secreted CCL5, which then promoted collagen synthesis via fibroblasts, thus contributing to tumor progression." (PMID 35241150, 2022). "Consistent with the changes in serum CCL2 and CCL5 in tumor-bearing mice, there were corresponding changes in ZO-1, Occludin and phosphorylated p38 protein levels in these premetastatic mouse lungs." (PMID 36438499, 2022). "Cxcr3 and Ccr5, the receptors for CXCL10 and CCL5, were broadly expressed on tumor-infiltrating lymphocytes, including regulatory T cells (Treg), gamma-delta (γδ) T cells, and NK cells." (PMID 36266311, 2022). "Anti-MAA-clonotypes showed expression of genes that have been previously associated with tumor-specificity and cytotoxicity (e.g., NKG7, CCL5, TIM3), as in a previous analysis of anti-MAA and neoantigen-specific clones in a scRNA-seq data set16." (PMID 36220826, 2022).
tumor (continued). "Future studies determining the underlying interactions between tumor and immune cells will help our understanding of how the CCR5/CCL5 axis plays a major role in T cell infiltration into PNETs." (PMID 36301668, 2022). "Although the exact molecular mechanism has not yet been clarified, it was found that PTH-AS expression in T47D cells upregulates STAT1 and its downstream cancer-promoting IRDS and CCL5, resulting in enhanced tumor malignancies." (PMID 35618021, 2022). "CCL5 plays a role in the recruitment and activation of immune cells, which means that CCL5 can be used as an adjuvant to enhance anti-tumor immunity through various protocols." (PMID 36387070, 2022). "After being stimulated by cancer cells, TA-MSCs can produce the chemokine CCL5, which in turn acts on tumor cells in a paracrine manner to induce their motility and metastatic ability." (PMID 36324128, 2022). "N2 type can promote the progression of tumors by expressing vascular endothelial growth factor and a variety of chemokines (CCL2, CCL5, etc.), can inhibit the anti-tumor activity of other immune cells, and can form cell clusters with circulating tumor cells." (PMID 36034356, 2022). "CCL5 can be found in cancer cells, CAFs, MSCs, MDSCs, TAMs, and anticancer tumour-infiltrating lymphocytes (TILs)." (PMID 35365161, 2022). "CCL5 is produced by tumor cells, while CXCL9 is produced by TAMs and DCs, which are dependent on antigen recognition and IFN-γ-specific induction." (PMID 35892835, 2022). "A growing body of evidence indicates the implication of the increased CCL5 level in BC progression and tumor metastasis promotion." (PMID 35725915, 2022). "The staining assay showed that CCL5 expression located in peri-tumor AT was related to LN and distant metastases, and OS in TNBC patients." (PMID 35701840, 2022). "Because of the elevated levels of the tumor-secreting chemokines CCL5 and CXCL10, autophagy inhibition increases the formation of NK cells in glioblastoma in vivo." (PMID 36300110, 2022). "Untreated WT mice (WT control) mostly died within 50 days after inoculation (median survival time: 41 days) and the median survival time of tumor-bearing CCL5−/− mice (CCL5−/− control) was 54 days, but all mice died because of tumor burden." (PMID 35327361, 2022). "The B16F10 cells produced large amounts of CCL5/RANTES, whereas the ex vivo s.c. tumour also secreted CCL2/MCP-1 and, at much lower levels, CCL3/MIP-1α and CCL4/MIP-1β." (PMID 36241867, 2022). "MSCs secrete inflammatory cytokines, including CCL-5 and IL-17B, and which promote tumor invasion and metastasis." (PMID 36439438, 2022). "CCL5 expression in the tumor cells regulates both EV biogenesis/secretion/cargo and macrophage EV-education toward a pro-metastatic phenotype." (PMID 34298673, 2021). "Our data suggest that CCL5 has a tumor-restricting effect by promoting infiltration of antitumor immune cells when coexpressed with high Flt3L levels." (PMID 33980589, 2021). "We found that MVC, a CCR5 (chemokine receptor for CCL5) antagonist, prevents the increased recruitment of cDC1s to the tumor on DNGR-1 blockade in the presence of Flt3L." (PMID 33980589, 2021). "Second, we examined gene expression levels for a selection of chemokines associated with T cell recruitment to the tumor, namely CCL4, CCL5, CXCL9, CXCL10." (PMID 33806316, 2021). "CCL5 is mainly secreted by T lymphocytes, macrophages, platelets, synovial fibroblasts, tubular epithelium, and tumor cells." (PMID 34771505, 2021). "Expression of tumor CCL5 regulates EV secretion and cargo that further alters macrophage phenotype to drive tumor metastasis." (PMID 34298673, 2021). "Since the role of eosinophils in tumors is also limited, intact CCL5 or CD26-processed CCL5 isoforms would most likely instigate a similar effect on tumor progression." (PMID 34503058, 2021).
tumor (continued). "Inflammatory mediators secreted by CAFs such as SDF-1, MCP-1/CCL2, IL-β, and RANTES/CCL5 induce immunosuppressive cells including myeloid-derived suppressor cells (MDSCs), regulatory T cells (Tregs), and tumor-associated macrophages (TAMs)." (PMID 34436224, 2021). "IFN-γ-neutralisation abrogated SCC regression, significantly reduced CD8+ T cell-infiltration into SCC, and significantly impaired the secretion of CXCL9, CXCL10 and CCL5 within the tumour microenvironment." (PMID 33925140, 2021). "CCL5 expression within the tumor increases the secretion of tumor EVs and alters the ability of EVs to educate macrophages." (PMID 34298673, 2021). "Pre-clinical modeling has shown that tumor-associated eosinophils express chemokines, such as CCL5, CXCL9, and CXCL10, which promote recruitment of tumor reactive CD8+ T cells into the tumor microenvironment." (PMID 34732251, 2021). "Specifically, studies have shown that tumor-derived CCL5 can recruit T-regulatory cells (T-regs) into the tumor, leading to CD8+ T-cell apoptosis." (PMID 34298673, 2021). "In this study, we analyzed the circulatory and tumor-associated levels of CCR5 and/or its ligands (CCL3, CCl4, CCL5) via ELISA and qRT-PCR/IHC, respectively." (PMID 32902795, 2021). "Lastly, we determined if intratumorally administered CCL5 was able to enhance the efficacy of anti-PD-L1 therapy using the same tumor model." (PMID 34030676, 2021). "Further IHC analysis showed higher expression of CCL5 and p-NF-κB in tumor specimens after PARPi therapy." (PMID 34108603, 2021). "Tumor expression or serum concentrations of CCL5, CCL25, or PD-L1 were determined with immunohistochemistry or ELISA." (PMID 34771505, 2021). "Our scRNAseq analysis also shows that the T cell populations activated by neo-aPD1 produces chemotactic factors that recruit DCs (XCL1, XCL2) and additional T cells (CCL5) into the tumor microenvironment." (PMID 34836966, 2021). "We showed that tumors expressing a deleted form of HIF-1α displayed increased levels of NK and CD8+ effector T cells in the tumor microenvironment, which was associated with high levels of CCL2 and CCL5 chemokines." (PMID 34155342, 2021). "For example, NK cells can recruit DCs into tumor microenvironment and enhance the anti-tumor immune activity through secreting CCL5 and XCL1." (PMID 33262461, 2021). "In the large majority of tumor types, Il12b, Ifng, Ccl4, Ccl5, Cxcl9, and Cxcl10 showed a significant positive correlation with infiltration of M1 macrophages, with Ccl3 displaying a lesser overall correlation." (PMID 34446712, 2021). "Monocytes from peripheral blood are recruited into the TME and differentiate into TAMs in response to chemokines, including CCL5 (secreted by M2-like macrophages), and growth factors produced by stromal and tumour cells." (PMID 34638423, 2021). "CD45‐immunoreactive cells in tumor tissues and adjacent healthy tissues have been found to be upregulated following CCL5 blockade." (PMID 33463063, 2021). "The CRC patients were then categorized into two groups according to the expression level of CTTCs (CXCL9, CXCL10, CXCL11, and CCL5) in tumor." (PMID 34539647, 2021). "Taken together, these suggest that circulating CCL5 levels at baseline relate to intrinsic tumour properties." (PMID 33100327, 2021). "CCL5 is also secreted by tumor cells in order to recruit Tregs to suppress pro-inflammatory effector T cells within the tumor microenvironment." (PMID 36474817, 2021). "The interaction between CCR5 and its ligand CCL5 supports tumor growth and invasion, and migration of MDSCs to the tumor site; tumor growth and invasiveness are suppressed by targeting the CCR5-CCL5 interaction." (PMID 34445615, 2021). "Some up-regulated genes including PPBP, OST4, PF4, GP1BB and CCL5 were related to tumor progression." (PMID 34722319, 2021). "This led us to test and validate the therapeutic potential of CCL5 treatment plus anti-PD-L1 in the preclinical MC38 tumor model." (PMID 34030676, 2021).
tumor (continued). "Several essential cytokines were also higher in the high-risk group, such as CCL5 (recruiting MDSC to tumor site), CCL22 (driving Treg recruitment into tumor site), and IL-10 (inhibiting cytokine synthesis)." (PMID 34961815, 2021). "CCL5 regulates both the secretion of EVs from tumor cells, as well as their ability to program macrophages." (PMID 34298673, 2021). "Overall, these experiments suggest that tumor CCL5 not only enhances the number of EVs but also alters the cargo of EVs." (PMID 34298673, 2021). "Conversely, reduction of CCL5 expression through either CRISPR-Cas9 (BM1 cells) or CRISPR-dCas9-KRAB (LMB cells) decreased TEM-mediated tumor cell invasion." (PMID 34298673, 2021). "Inhibition of autophagy (i.e., by shRNA silencing Becn1) induces a massive CCL5‐dependent infiltration of NK cells into melanoma tumors, thereby reducing tumor volume." (PMID 34459017, 2021). "For Ccl5, Ccl22, Ccl27a, Ccl28, and Cxcl12, chemokines known to exert pro-tumor effects, substantially higher levels were noted in the liver." (PMID 33985562, 2021). "Many of these tumor-infiltrating T cells highly expressed chemotactic genes, such as CCL5 and XCL1, that can attract additional T cells and professional antigen presenting cells (e.g., dendritic cells) into the tumor microenvironment." (PMID 34836966, 2021). "Together, these data suggest that intratumorally administered CCL5 altered the tumor microenvironment, including by recruiting cytotoxic lymphocytes." (PMID 34030676, 2021). "The expression of CXCL9, CXCL10, and CXCL11 except for CCL5 was significantly higher in the tumor compared with the adjacent normal tissues (p = 0.0707, p = 0.0001, p < 0.0001, and p = 0.4207)." (PMID 34539647, 2021). "This is consistent with a recent publication reporting the crucial role of CCL5 produced by malignant cells to stimulate the penetration of tumor infiltrating lymphocytes in human malignancies and murine tumor models." (PMID 33664349, 2021). "Constitutively active STAT3 signaling in tumor cells has been shown to downregulate chemokine expression, including CCL5 and CXCL10, which are functionally responsible for T cell recruitment." (PMID 33777927, 2021). "OVT can increase the access of TILs and CAR-T cells to the tumor by altering the tumor matrix and increasing the chemokines such as CCL5." (PMID 33546172, 2021). "C3aR−/− mice showed a change in the proportions of different leukocyte subpopulations in tumour infiltrates and had increased CCL5 in lysates from tumours." (PMID 33494138, 2021). "We found that this was due to diminished CCL5 expression, which in turn impaired dendritic cell recruitment to the tumor microenvironment and thus led to ineffective CD8+ T cell tumor clearance." (PMID 33981303, 2021). "Together, these results suggest that increased CCL5 expression in tumors leads to increased and altered EVs from tumor cells." (PMID 34298673, 2021). "At the tumor site, MSCs infiltrate into the stroma and produce bioactive molecules such as CCL5, IL-6, SDF-1 and TGFβ, which promote tumor growth and/or distant metastasis to secondary organs, such as the lungs." (PMID 34359821, 2021). "MDSCs produce the CCR5 ligands CCL4 and CCL5, which recruit Tregs to tumor tissues by CCR5 receptors highly expressed on Treg surface." (PMID 34527668, 2021). "We found that almost exclusive expression of CCL5 in CTCs compared with primary tumor cells (median, 63% vs 2%, P = 0.021)." (PMID 34215748, 2021). "Here we show that downregulation of RhoA expression rescued the RKIP-mediated inhibition of CCL5 expression and F4/80+ cells tumor infiltration." (PMID 34465801, 2021). "In the tumor microenvironment, tumor cells recruit normal cells by secreting CCL5 and training them to become immunosuppressive tumors." (PMID 34777462, 2021).